NTS (neurotensin)
Diseases named in the same sentence as NTS in open-access papers (continued):
Sharing a sentence is not in itself a finding about the gene and the disease.
diabetes (8 papers, 2017 to 2025). "The level of proneurotensin, the propeptide of neurotensin, was reported to be related to the risk of incident diabetes mellitus in a prospective cohort study." (PMID 28728579, 2017). "Future studies focusing on causality and genetic variations within the neurotensin system across ethnicities could provide increased understanding of mechanisms involved contributing to the excess diabetes risk that the Middle Eastern population is exposed to." (PMID 31541150, 2019). "Bone health is affected by diabetes through different mechanisms, among others, and particular attention should be kept towards VDR polymorphisms, Vitamin D, incretins, GLP-2, neurotensin, asprosin, irisin, and TXNIP levels." (PMID 40943066, 2025). "Taken together, neurotensin and xenin have the combined ability to modulate and augment the incretin effect, with obvious therapeutic implications for diabetes." (PMID 34370015, 2021). "In our study, plasma levels of sortilin, a receptor for neurotensin, were related to diabetes mellitus and insulin resistance." (PMID 28728579, 2017). "This would suggest that shorter neurotensin and xenin peptides which are easier to synthesise and formulate, may have therapeutic promise for diabetes." (PMID 34370015, 2021). "Consequently, the role of Vitamin D, Incretins, Glucagon-like peptide-2 (GLP-2), neurotensin, asprosin, irisin, and Thioredoxin-interacting protein (TXNIP) will be described considering the interplay between diabetes and bone health." (PMID 40943066, 2025).
lung cancer (8 papers, 2010 to 2022). A malignant neoplasm involving the lung. "Several reports implicate neurotensin in numerous detrimental functions linked to neoplastic progression of several cancer types, including pancreatic, prostate, colon and lung cancers." (PMID 20830311, 2010). "High expression of NTS and its receptor NTSR1 are identified in lung cancer, compared with normal cells." (PMID 32121246, 2020). "Here we highlight the cellular mechanisms activated by Neurotensin (NTS) and its high affinity receptor (NTSR1) contributing to lung cancer cell aggressiveness." (PMID 25249545, 2014). "Neurotensin (NTS) and its high affinity receptor (NTSR1) are up regulated in 60% of lung cancers." (PMID 25249545, 2014).
pancreatic cancer (8 papers, 2011 to 2023). "Neurotensin has been found to be produced by some P-NETs26 and to stimulate mitogenic signaling pathways and DNA synthesis in human pancreatic cancer cell lines." (PMID 32884006, 2020). "It appears to be clear that NT-R (especially the type 1 NT-R (also named NTS1)) mediate a proliferative action of neurotensin in pancreatic cancer and also in other tumors." (PMID 25859423, 2015). "We have examined signalling pathways activated by neurotensin in colorectal and pancreatic carcinoma cells." (PMID 21961726, 2011). "Therefore, the use of neurotensin analogs has been proposed as strategy for the antiproliferative treatment of pancreatic cancer." (PMID 25859423, 2015). "Neuropeptides like bombesin, cholecystokinin, neuromedin N, neurotensin (NT), gastrin-releasing peptide and pituitary adenylate cyclase activating peptide stimulate growth and/or other cellular functions in various tumor types, including pancreatic cancer." (PMID 24212612, 2011). "There is increasing evidence that neurotensin (NT) and neurotensin receptors (NTR) play critical roles in the growth and survival of pancreatic neoplasms." (PMID 37188192, 2023).
depression (7 papers, 2020 to 2024). "Adjusted for sex, age and depression, neurotensin was negatively associated with MoCA score (r=−0.257, p=0.044), pannexin-1 was positively associated with the mean erroneous distance in the BVAT (r=0.270, p=0.033)." (PMID 38803679, 2024). "A recent study reported a potential association between plasma neurotensin and the number of lifetime suicide attempts in depressive patients, with the result of a strong positive correlation further suggesting an involvement of neurotensin in the pathogenesis of depression." (PMID 33664656, 2021). "We hypothesize that comparing salivary OXT, alpha-MSH, beta-endorphin, neurotensin, and substance P in patients with depression and controls could be as effective as comparing their serum levels." (PMID 39347144, 2024). "Studies conducted in recent decades suggest that the beneficial influence of DS on depression might be caused by alterations in the synthesis of neurotrophins; literature on this subject covers primarily BDNF, while the role of other NTs remains elusive." (PMID 38519465, 2024). "Other neuropeptides, including neurotensin and neuropeptide Y (NPY), have been shown to be involved in the pathogenesis of depression." (PMID 33071750, 2020). "Although the interacting mechanisms among ghrelin, neurotensin, and NPY in AD-related depression remain to be examined, neurotensin and NPY, at least, seem to be mediating some AD-related depression-like behaviors by interacting with ghrelin." (PMID 33071750, 2020).
colorectal cancer (6 papers, 2015 to 2025). A primary or metastatic malignant neoplasm that affects the colon or rectum. "In vitro study published in 2015, focusing on human colorectal cancer cell lines corresponding to different colorectal cancer stages, showed variable NTS and NTSR1 expressions, no expression of NTSR2 and constant NTSR3 expression." (PMID 33268796, 2020).
glioma (5 papers, 2014 to 2024). A benign or malignant brain and spinal cord tumor that arises from glial cells (astrocytes, oligodendrocytes, ependymal cells). "High expression of neurotensin/neurotensin 1 receptors is related to poor prognosis in patients with gliomas." (PMID 39063232, 2024). "Neurotensin, through the neurotensin 1 receptor, favors the proliferation of glioma cells by blocking miR-29b-1/miR-129-3p." (PMID 39063232, 2024). "Glioma growth is blocked when the neurotensin/neurotensin 1 receptor system or the Wnt/β-catenin pathway is pharmacologically blocked." (PMID 39063232, 2024). "Neurotensin, acting via this receptor, promotes the proliferation and invasion of glioma cells." (PMID 39063232, 2024). "The following peptides, through their respective receptors, promote glioma progression (proliferation, migration, invasion, and angiogenesis): AMD, angiotensin II, GRP, bradykinin, CCK, endothelin, neuromedin B, neurotensin, and substance P." (PMID 39063232, 2024). "In glioma grade III, highly activated DEGs included CFAP45, PLBD1, RASSF9, IGKV3-11, IGKV1-5, and NTS, while highly downregulated DEGs included NPAS4 and LINC01007." (PMID 33948562, 2021). "Yi and colleagues found that glioma-initiating cells produced CCL2, CCL5, VEGF-A, and neurotensin at higher levels than the glioma cells; these findings suggest that CSCs play an important role in TAM recruitment by secreting macrophage chemoattractants." (PMID 25125485, 2014).
Insulin resistance (5 papers, 2017 to 2023). Increased resistance towards insulin, that is, diminished effectiveness of insulin in reducing blood glucose levels. "Moreover, we found that neurotensin expression was increased in women with high insulin resistance." (PMID 35625760, 2022). "Recent study results have shown that increased plasma neurotensin levels identifies the presence and severity of NAFLD in dysmetabolic individuals through insulin resistance related mechanisms." (PMID 31541150, 2019).
type 2 diabetes (5 papers, 2021 to 2023). "Increased plasma levels of pro-neurotensin (pro-NT), a stable precursor fragment of NT, are associated with an increased risk of type 2 diabetes mellitus (T2DM), cardiovascular disease, and death." (PMID 34200577, 2021).
autistic disorder (3 papers, 2010 to 2019). "There are a few studies about neurotensin and autism, and they report that autism increases neurotensin serum levels in children with autism." (PMID 31036753, 2019). "Beta-endorphin, neurotensin, oxytocin and substance P plasma levels were studied because of their relationship with autism." (PMID 31036753, 2019). "Neurotensin levels have been found to be increased in the sera of 3-year old and 6–12 year-old children with autism." (PMID 31036753, 2019). "Recently, serum neurotensin levels in children with autistic disorder have been found to be higher than those of normal children." (PMID 20920308, 2010). "Neurotensin is known to intensify neuronal NMDA-mediated glutamate signaling, which may cause apoptosis in autism." (PMID 20920308, 2010). "Targeting neurotensin might be a possible novel approach for the treatment of autism." (PMID 20920308, 2010). "Future studies focusing on the central nervous system, especially for brain neurotensin levels and NTS1 and NTR3/sortilin receptors would be interesting for a better understanding of the mechanisms involved with ASD and neurotensin, including as a potential therapeutic target for autism." (PMID 31036753, 2019).
celiac disease (3 papers, 2015 to 2021). An autoimmune genetic disorder with an unknown pattern of inheritance that primarily affects the digestive tract. "It was reported in previous studies that hormone neurotensin increased in untreated celiac disease patients." (PMID 33614356, 2021). "Seven genes were down-regulated in the biopsies of celiac disease patients, among them NTS down-regulated 3.6 fold and the INSR, APPL2, ADCY9, GLS, HSPB1 and KIF13A 1.5-2.2 fold in the patient group (p < 0.001)." (PMID 26123480, 2015).
cognitive deficits (3 papers, 2019 to 2025). "Neurotensin, associated with cognitive deficits, increased in both cherry and placebo groups but was significant only in the placebo group (p = 0.007)." (PMID 40077655, 2025). "Above all, our results support the possibility that plasma neurotensin has a central role in cognitive function, and it has the potential to be the treatment target for improving cognitive deficit in severe mental illness." (PMID 37275985, 2023). "We previously reported an unchanged abundance of Δ A. hadrus in the placebo group, suggesting that increased neurotensin levels might correlate with an unchanged abundance of A. hadrus, potentially contributing to cognitive deficits." (PMID 40077655, 2025). "Exposure of rats to LPS during gestation induced cognitive deficits in the young offspring, elevated BDNF levels and decreased neurotensin levels." (PMID 31036753, 2019). "Although DSC consumption did not decrease neurotensin levels, it helped prevent a significant increase observed in the placebo group, suggesting the protective effects of DSC drink intake against cognitive deficits related to learning and memory processes in obese subjects." (PMID 40077655, 2025).
metabolic syndrome (3 papers, 2023). A cluster of metabolic risk factors for CARDIOVASCULAR DISEASES and TYPE 2 DIABETES MELLITUS. "A study found that pro-neurotensin/neuromedin N (pro-NT/NMN), another NAD+ precursor, was positively associated with incident metabolic syndrome (MetS), which is consistent with our findings of the effect of NAD+ on hyperuricemia and NAFLD." (PMID 37152934, 2023).
neuroendocrine tumor (3 papers, 2015 to 2025). "Notably, an increase in TRPM8 expression was observed in neuroendocrine tumor cells, and this rise was associated with an increased release of neurotensin." (PMID 38339011, 2024). "For example, TRPM8 channels regulate neurotensin secretion in neuroendocrine tumor cells)." (PMID 38339011, 2024). "Neurotensin (NTS), localized predominantly to the small bowel, stimulates the growth of a variety of cancers, including neuroendocrine tumors (NETs), mainly through its interaction with the high-affinity NTS receptor 1 (NTSR1)." (PMID 26298774, 2015).
Nonalcoholic Fatty Liver Disease (3 papers, 2021 to 2024). "Recently, rising evidence has demonstrated the role of the intestinal hormone Neurotensin (NT) in the development of obesity and its related cardio-metabolic disorders such as type 2 diabetes, non-alcoholic fatty liver disease (NAFLD), and CVDs6–12." (PMID 38956152, 2024). "Recent studies suggest a link between pro-neurotensin (pro-NT) and nonalcoholic fatty liver disease (NAFLD), but the published data are conflicting." (PMID 34200577, 2021).
Alzheimer disease (2 papers, 2018 to 2022). A progressive, neurodegenerative disease characterized by loss of function and death of nerve cells in several areas of the brain leading to loss of cognitive function such as memory and language. "Neurotensin influences the formation of senile plaques and therefore is associated with the pathogenesis of Alzheimer's disease through different pathways." (PMID 30687008, 2018). "In summary, the levels of neurotensin and neurotensin receptors decrease in many brain areas of Alzheimer's disease." (PMID 30687008, 2018). "The levels of neurotensin and neurotensin receptors change in several brain regions of Alzheimer's disease patients." (PMID 30687008, 2018). "Neurotensin plays multiple effects in central nervous system and is involved in the pathophysiology of several central nervous system disorders, including schizophrenia, Parkinson's disease, as well as Alzheimer's disease." (PMID 30687008, 2018). "Previous studies revealed a decreased level of neurotensin in the septum, suprachiasmatic nucleus and amygdala, and a low level of neurotensin receptors in the entorhinal area, dentate gyrus and temporal gyrus of Alzheimer's disease." (PMID 30687008, 2018). "Numerous studies have indicated that the neuropeptides including ghrelin, neurotensin, pituitary adenylate cyclase-activating polypeptide (PACAP), neuropeptide Y, substance P and orexin are closely related to the pathophysiology of Alzheimer's disease." (PMID 30687008, 2018). "In this review article, we provide a description of recent advances of neuropeptides including ghrelin, neurotensin, PACAP, neuropeptide Y, substance P and orexin in Alzheimer's disease." (PMID 30687008, 2018). "Recent studies revealed that many neuropeptides including ghrelin, neurotensin, pituitary adenylate cyclase-activating polypeptide (PACAP), neuropeptide Y, substance P, and orexin may be associated with the pathophysiology and potential therapy of Alzheimer's disease." (PMID 30687008, 2018).
atherosclerosis (2 papers, 2021 to 2022). A disease characterized by the build-up of fatty material and calcium deposition in the arterial wall resulting in partial or complete occlusion of the arterial lumen. "More studies are needed to further investigate the pathophysiological role of neurotensin in early stages of atherosclerosis and HF and its value in risk prediction and as a potential therapeutic target." (PMID 35345492, 2022).
autism spectrum disorder (2 papers, 2013 to 2024). A spectrum of developmental disorders that includes autism, and Asperger syndrome. "In the patients of autism spectrum disorders (regarded as neurodevelopmental disorders), serum concentration of neurotensin is elevated and trigger mast cells to release inflammatory factors, which stimulate microglia proliferation and activation, leading to disruption of neuronal connectivity." (PMID 38803679, 2024).
bladder cancer (2 papers, 2015 to 2018). "In previous studies we showed that a tetra-branched form of neurotensin, called NT4, has extraordinary selectivity towards different human tumors (i.e. colon, pancreas and urinary bladder cancer) and is easily coupled to chemical entities or liposomes for cancer cell killing or imaging." (PMID 29501065, 2018).
carcinoid tumor (2 papers, 2007 to 2010). A slow growing neuroendocrine tumor, composed of uniform, round, or polygonal cells having monotonous, centrally located nuclei and small nucleoli, infrequent mitoses, and no necrosis. "Other hormones and biochemical substances secreted from carcinoid tumors include corticotropin, histamine, dopamine, substance P, neurotensin, prostaglandins and kallikrein." (PMID 21144059, 2010).
ductal pancreatic adenocarcinoma (2 papers, 2015 to 2017). "Using in vitro receptor autoradiography with 125I-[Tyr3]-neurotensin, NT-R were investigated in 18 primaries and 23 liver metastases of pancreatic ductal carcinomas as well as in 19 PanIN lesions." (PMID 25859423, 2015). "It would be equally important to be able to treat the patients that have a receptor-positive carcinoma by giving them a radiotherapeutic dose of the radiolabeled neurotensin; many of the patients diagnosed with pancreatic ductal carcinomas already have or will soon have metastatic disease." (PMID 25859423, 2015).
glioblastoma (2 papers, 2018 to 2024). The most malignant astrocytic tumor (WHO grade IV). "Glioblastoma growth is inhibited in in vitro and in vivo experiments when the Wnt/β-catenin pathway or the neurotensin/neurotensin 1 receptor system is pharmacologically blocked." (PMID 39063232, 2024). "Neurotensin controls, via activation of the interleukin-8/ERK/CXXC1/STAT3 pathway, the stem-like traits of glioblastoma stem cells." (PMID 39063232, 2024).
hepatocellular carcinoma (2 papers, 2013 to 2023). A malignant tumor that arises from hepatocytes. "Neurotensin/IL-8 pathway was also demonstrated to orchestrate local inflammatory response and tumor invasion by inducing M2 polarization of tumor-associated macrophages in mouse hepatocellular carcinoma." (PMID 37231519, 2023).
melanoma (2 papers, 2018 to 2024). A malignant, usually aggressive tumor composed of atypical, neoplastic melanocytes. "In this study, six genes (ADCYAP1R1, GPI, IFITM1, KIR2DL4, LIF, and NTS) were identified as being closely associated with prognosis among a pool of 1793 melanoma-related genes." (PMID 38217549, 2024). "In this study, six genes (ADCYAP1R1, GPI, IFITM1, KIR2DL4, LIF, and NTS) that exhibited strong correlation with the prognosis of melanoma patients were identified." (PMID 38217549, 2024). "Six genes closely associated with the prognosis of melanoma patients, including ADCYAP1R1, GPI, IFITM1, KIR2DL4, LIF and NTS, were elected to fabricate a prognosis model." (PMID 38217549, 2024). "Our findings indicate that ADCYAP1R1, GPI, and NTS may contribute to a poor prognosis in melanoma patients, while IFITM1, KIR2DL4, and LIF are more likely to be associated with a better prognosis in individuals with melanoma." (PMID 38217549, 2024).
mood disorder (2 papers, 2023 to 2024). A cognitive disorder a disturbance in which the person's mood is hypothesized to be the main underlying feature. "The substantial decrease in neurotensin suggests it could serve as a valuable biomarker for developing gender-specific diagnostic tools or treatments for mood disorders." (PMID 39347144, 2024).
neuroblastoma (2 papers, 2009 to 2025). Neuroblastoma (NB) is the most common solid, extracranial childhood tumor. "Peptides (angiotensin II, neuropeptide Y, neurotensin, substance P) act as oncogenic agents in neuroblastoma, whereas others (adrenomedullin, corticotropin-releasing factor, urocortin, orexin) exert anticancer effects against neuroblastoma." (PMID 40331938, 2025).
amyloid (1 paper, 2018). "The amyloid plaque density in the occipital cortex is negatively associated with the neurotensin-positive neurons in the suprachiasmatic nucleus." (PMID 30687008, 2018).
anemia (1 paper, 2019). A reduction in the number of red blood cells, the amount of hemoglobin, and/or the volume of packed red blood cells. "Anemia increased neurotensin in the normal-Fe groups fed fermented cow milk (p < 0.001)." (PMID 31591353, 2019).
asthma (1 paper, 2021). "Their impact on asthma symptoms can be either soothing, as for neurotensin, or aggravating, as for neuropeptide Y." (PMID 34948451, 2021).
Cirrhosis (1 paper, 2021). A chronic disorder of the liver in which liver tissue becomes scarred and is partially replaced by regenerative nodules and fibrotic tissue resulting in loss of liver function. "Even more, the Neurotensin (NTS) rs1800832 variant predisposes to cirrhosis and HCC in NAFLD patients likely by affecting NTS protein activity." (PMID 34680476, 2021).